DMD (dystrophin)
Diseases named in the same sentence as DMD in open-access papers (continued):
Sharing a sentence is not in itself a finding about the gene and the disease.
Duchenne muscular dystrophy (continued). "In contrast, Duchenne muscular dystrophy (DMD) is a severe pediatric neuromuscular disorder caused by dystrophin gene mutations that result in absent or defective dystrophin protein within muscle fibers." (PMID 41302155, 2025). "Dystrophinopathy, which includes Duchenne muscular dystrophy (DMD, MIM 310200) and Becker muscular dystrophy (BMD, MIM 300376), is an X‐linked recessive neuromuscular disorder that occurs from mutations in the DMD gene and its prevalence ranges from of 15.9 to 19.5 per 100,000 live male births." (PMID 39575648, 2025). "Łoboda, Chamberlain, and Dulak review genetic strategies for Duchenne muscular dystrophy, focusing on exon skipping, gene replacement, and CRISPR-Cas9 editing to restore dystrophin or upregulate utrophin." (PMID 41328300, 2025). "Duchenne muscular dystrophy (DMD) is caused by pathogenic variants in the X-linked DMD gene, resulting in the absence of functional dystrophin and continuous muscle damage, starting at birth." (PMID 41288941, 2025). "Duchenne muscular dystrophy (DMD) is a progressive, X‐linked muscle degenerative disorder characterized by the absence of dystrophin protein." (PMID 40366239, 2025). "Duchenne muscular dystrophy (DMD) and the allelic Becker muscular dystrophy (BMD) are among the most common and severe inherited neuromuscular disorders, caused by pathogenic variants in the DMD gene located on chromosome Xp21.2." (PMID 41595440, 2025). "In Duchenne muscular dystrophy (DMD), iPSC-derived myocytes allow mechanistic studies of muscle degeneration, and gene editing has restored dystrophin expression in vitro, highlighting therapeutic potential." (PMID 41210051, 2025). "Dystrophinopathies, including Duchenne muscular dystrophy (DMD) and Beck muscular dystrophy (BMD), predominantly arise from variants in the X-chromosomal DMD (dystrophin) gene, leading to loss of dystrophin, which disrupts the critical dystrophin–glycoprotein complex (DGC)." (PMID 40868246, 2025). "Duchenne muscular dystrophy (DMD) is an X-linked devastating disease caused by a lack of dystrophin which results in progressive muscle weakness." (PMID 39919154, 2025). "Duchenne muscular dystrophy (DMD) is caused by DMD mutations leading to a complete or almost complete absence of the dystrophin protein." (PMID 40552660, 2025). "Duchenne muscular dystrophy (DMD) is a devastating disorder caused by pathogenic variants in the dystrophin gene resulting in the absence of a functional dystrophin protein." (PMID 40695995, 2025). "Among them, there are Duchenne muscular dystrophy (DMD), which depends on defects of the dystrophin gene, and congenital muscular dystrophy (CMD), which is linked to mutations hitting laminin α2." (PMID 40422224, 2025). "Duchenne muscular dystrophy (DMD) is a degenerative neuromuscular disease caused by a lack of functional dystrophin." (PMID 39519374, 2024). "For Duchenne muscular dystrophy (DMD) which can be caused by any 1 of the more than 2000 different mutations in the DMD gene, cell therapy offers potential benefits regardless of the exact genetic mutation which can vary from patient to patient." (PMID 38425500, 2024). "Duchenne muscular dystrophy (DMD) is a devastating X-linked neuromuscular disorder caused by various defects in the dystrophin gene and still no universal therapy." (PMID 38762732, 2024). "Approximately 1 : 3500 males are affected by Duchenne muscular dystrophy (DMD), a severe X-linked recessive disorder that develops when the dystrophin protein is deficient or absent, leading to the weakness of the muscle membrane and subsequent degradation." (PMID 39328357, 2024). "Duchenne muscular dystrophy (DMD) is a degenerative neuromuscular disease that primarily affects males and is caused by reduced or absent dystrophin." (PMID 38525359, 2024). "In Duchenne Muscular Dystrophy (DMD), H19 interaction with dystrophin is impaired, resulting in the degradation of dystrophin and muscle degeneration." (PMID 39416175, 2024).
Duchenne muscular dystrophy (continued). "Dystrophinopathies are a spectrum of muscle genetic diseases caused by alterations in the Dystrophin gene, and Duchenne muscular dystrophy (DMD) is the most severe form caused by the total absence of the coded protein." (PMID 38691608, 2024). "Golodirsen, the second FDA-approved drug for Duchenne muscular dystrophy (DMD), gained approval on 12 December 2019 based on increased dystrophin expression." (PMID 38983605, 2024). "We studied the impact of disease mutations using multiple cell lines with or without mutations in the dystrophin gene leading to Duchenne Muscular Dystrophy (DMD)-linked dilated cardiomyopathy." (PMID 38926342, 2024). "In contrast, patients with Duchenne muscular dystrophy (DMD), who lack dystrophin and NOS1 and, at least in the skeletal muscle, have raised miR-31 expression, do not have increase susceptibility to AF in the absence of left ventricular (LV) dysfunction." (PMID 38270932, 2024). "Dystroglycan is a central component of the dystrophin-glycoprotein complex (DGC) known primarily for its role in the etiology of neuromuscular diseases including Duchenne muscular dystrophy (DMD), limb-girdle muscular dystrophy (LGMD), and congenital muscular dystrophy (CMD)." (PMID 38179984, 2024). "For example, gene editing techniques, such as exon skipping, have demonstrated potential in conditions such as Duchenne muscular dystrophy (DMD), in which mutations in the dystrophin gene result in the lack of the dystrophin protein." (PMID 37894902, 2023). "Duchenne muscular dystrophy is an X-linked genetic disorder caused by the absence of dystrophin (DMD), a gene that encodes a 427-kD protein that links the sarcomere and the extracellular matrix." (PMID 36980233, 2023). "Duchenne muscular dystrophy (DMD) is caused by DMD gene mutations, resulting in absence of functional dystrophin protein." (PMID 37005891, 2023). "Several groups have demonstrated the restoration of cardiac dystrophin levels using AAV-mediated delivery of Cas9 and a single gRNA in mouse models of Duchenne muscular dystrophy DMD." (PMID 37408197, 2023). "Duchenne muscular dystrophy (DMD) is caused by an out-of-frame mutation in the DMD gene that results in the absence of a functional dystrophin protein, leading to a devastating progressive lethal muscle-wasting disease." (PMID 37228827, 2023). "Duchenne muscular dystrophy (DMD, OMIM # 310200) is an X-linked recessive disorder with a prevalence of 4.78 per 100,000 males, caused by mutations of the DMD gene, which is expressed in muscle sarcolemma and encodes the muscle protein, dystrophin." (PMID 37615381, 2023). "Duchenne muscular dystrophy (DMD) is caused by genetic mutations leading to lack of dystrophin in skeletal muscle." (PMID 37000843, 2023). "In cell and animal models of Duchenne muscular dystrophy (DMD), exon skipping can therapeutically restore dystrophin protein expression, highlighting an alternative therapeutic strategy." (PMID 37215149, 2023). "Duchenne muscular dystrophy (DMD) is an X-linked muscular disease which is caused by the absence of dystrophin." (PMID 36869352, 2023). "Duchenne muscular dystrophy (DMD) is an X-linked neuromuscular disorder caused by lack of functional full-length dystrophin protein expression." (PMID 37834164, 2023). "Similar high-throughput methods using the In-Cell Western (ICW) technology were previously successfully developed to quantify dystrophin to evaluate exon skipping efficiency after antisense oligonucleotide treatment in Duchenne Muscular Dystrophy (DMD) patients’ myotubes." (PMID 37887288, 2023). "Duchenne muscular dystrophy (DMD) is an X-linked progressive muscle-wasting disease caused by the lack of the cytoskeletal protein dystrophin." (PMID 37208786, 2023).
Duchenne muscular dystrophy (continued). "The dystrophin–glycoprotein complex (DGC) has well-described roles in normal force transmission, especially in the context of muscle diseases such as Duchenne muscular dystrophy, with evidence accumulating for other roles in anabolic and vascular signalling." (PMID 37932834, 2023). "In this study, we reported an asymptomatic male with duplication of exons 56–61 in the DMD gene through ECS using whole-exome sequencing (WES), which was also detected in a male patient diagnosed with typical Duchenne muscular dystrophy (DMD)." (PMID 35615378, 2022). "Duchenne muscular dystrophy (DMD) is characterized by the absence of the full-length membrane associated cytoskeletal protein, dystrophin, leading to severe muscle weakness, cardiomyopathy, and premature death." (PMID 36742199, 2022). "Duchenne muscular dystrophy (DMD) is an X-linked muscle disease caused by a complete lack of dystrophin, which stabilizes the plasma membrane of myofibers." (PMID 36258243, 2022). "Duchenne muscular dystrophy (DMD) is the most common and severe muscle disorder caused by a mutation in chromosome X (region Xp 21.2) that leads to an absence of the protein dystrophin." (PMID 35562874, 2022). "Duchenne muscular dystrophy (DMD), a neuromuscular disorder caused by the absence of the dystrophin-encoding DMD gene, is frequently associated with a broad range of symptoms of brain origin." (PMID 34101068, 2022). "A demonstration of the potential of this method has been observed in the treatment of Duchenne muscular dystrophy (DMD, OMIM #310200), where the use of CRISPR/Cas9 in patient’s myoblasts restored the expression of dystrophin." (PMID 35456445, 2022). "Duchenne muscular dystrophy (DMD) is an X-linked recessively inherited genetic disease caused by the absence of dystrophin due to loss-of-function variants in DMD gene." (PMID 35886062, 2022). "Duchenne muscular dystrophy (DMD) is a lethal, degenerative muscle disorder caused by mutations in the DMD gene, leading to severe reduction or absence of the protein dystrophin." (PMID 34737451, 2022). "The most common and severe type of dystrophinopathy, Duchenne Muscular Dystrophy (DMD), is characterized by a complete disruption of the genetic code in the dystrophin protein and has an estimated birth prevalence of 1 per 3500 to 1 per 9300 males (OMIM: 310,200, ORPHA: 98,896)." (PMID 36421868, 2022). "Duchenne Muscular Dystrophy (DMD) is caused by the absence of dystrophin and a disruption of the associated glycoprotein complex." (PMID 36142754, 2022). "The lack of functional dystrophin is the primary cause of Duchenne muscular dystrophy (DMD) and is responsible for irreversible muscle weakening, with cardio-respiratory failure being the most common cause of premature death." (PMID 35273230, 2022). "Duchenne muscular dystrophy (DMD) and Golden Retriever muscular dystrophy (GRMD) are genetically homologous, phenotypically analogous degenerative muscle diseases caused by mutations in the DMD gene, which encodes the dystrophin protein." (PMID 35252412, 2021). "Duchenne muscular dystrophy (DMD), caused by a lack of functional dystrophin, is characterized by progressive muscle degeneration." (PMID 33925757, 2021). "Dystrophin is an integral sarcolemmal protein essential for muscle contraction and maintenance, absence of which leads to the devastating muscle wasting disease Duchenne muscular dystrophy (DMD)." (PMID 34389686, 2021). "Duchenne muscular dystrophy (DMD), an X-linked recessive condition, is a rare genetic disorder caused by the absence of functional dystrophin proteins due to gene mutations." (PMID 34071811, 2021). "For example, in the most common early onset severe form, named Duchenne muscular dystrophy (DMD), out-of-frame DMD mutations disrupt full mRNA translation, thus no dystrophin can be expressed." (PMID 34445659, 2021). "The consequences of dystrophin reduction can be seen in Duchenne Muscular Dystrophy (DMD)." (PMID 33927797, 2021).
Duchenne muscular dystrophy (continued). "Duchenne muscular dystrophy (DMD) is a common and severe X-linked myopathy, characterized by muscle degeneration due to altered or absent dystrophin." (PMID 33479270, 2021). "Duchenne muscular dystrophy (DMD) is the most common and most severe MD and it is characterized by a complete lack of dystrophin due to mutations in the DMD gene." (PMID 33801069, 2021). "Duchenne muscular dystrophy (DMD) is an X-linked neuromuscular disease caused by a pathogenic disruption of the DYSTROPHIN gene that results in non-functional dystrophin protein." (PMID 34357020, 2021). "Duchenne muscular dystrophy (DMD) is a X-linked recessive disorder that arises from mutations in the dystrophin gene causing absent or truncated dystrophin protein." (PMID 33663533, 2021). "Duchenne muscular dystrophy (DMD) is a progressive hereditary muscular disease caused by a lack of dystrophin, leading to membrane instability, cell damage, and inflammatory response." (PMID 33918694, 2021). "Duchenne muscular dystrophy (DMD) is a lethal X-linked recessive disorder caused by mutations in the DMD gene and the subsequent lack of dystrophin protein." (PMID 34884867, 2021). "Duchenne muscular dystrophy (DMD, OMIM 310200), the most severe and the most common adult form of muscular dystrophy in humans, is caused by a lack of functional dystrophin due to mutations in the dystrophin gene (DMD)." (PMID 33468200, 2021). "The most lethal end of this spectrum, Duchenne muscular dystrophy (DMD), generally arises from mutations that disrupt the translational reading frame and result in an absence of dystrophin." (PMID 33466756, 2021). "Duchenne muscular dystrophy (DMD) is an X-linked disease caused by mutations in DMD gene translating in lack of functional dystrophin and resulting in susceptibility of myofibers to rupture during contraction." (PMID 34680138, 2021). "In Duchenne muscular dystrophy (DMD), the absence of dystrophin from the dystrophin-associated protein complex (DAPC) causes muscle membrane instability, which leads to myofiber necrosis, hampered regeneration, and chronic inflammation." (PMID 33808305, 2021). "Dystrophinopathies, including Duchenne muscular dystrophy (DMD), Becker muscular dystrophy (BMD), and X-linked dilated cardiomyopathy (XLDCM), are genetic muscle dystrophies of X-linked inheritance caused by mutations in the DMD gene on the X chromosome." (PMID 32504006, 2020). "Duchenne muscular dystrophy (DMD) is a X-linked neuromuscular disorder caused by mutations in the DMD gene, leading to a lack of dystrophin expression, a cytoskeletal protein mainly expressed in muscles, but also in other tissues like retina and brain." (PMID 32160266, 2020). "In Duchenne muscular dystrophy (DMD) patients, absence of dystrophin causes muscle wasting by impacting both the myofiber integrity and the properties of muscle stem cells (MuSCs)." (PMID 32722643, 2020). "The primary molecular endpoint for many Duchenne muscular dystrophy (DMD) clinical trials is the induction, or increase in production, of dystrophin protein in striated muscle." (PMID 32303261, 2020). "Duchenne muscular dystrophy (DMD) is the most severe and frequent muscular dystrophy with most patients having little, if any, detectable dystrophin within muscle." (PMID 32636760, 2020). "Duchenne muscular dystrophy (DMD) is a life-threatening neuromuscular disease caused by the lack of dystrophin, resulting in progressive muscle wasting and locomotor dysfunctions." (PMID 32988972, 2020). "Duchenne muscular dystrophy (DMD) is a devastating genetic muscular disorder with no effective treatment that is caused by the loss of dystrophin." (PMID 32430065, 2020). "Duchenne muscular dystrophy (DMD) is an X-linked genetic disease characterized by progressive muscle weakness due to a lack of dystrophin." (PMID 32693782, 2020).
Duchenne muscular dystrophy (continued). "Duchenne muscular dystrophy (DMD), caused by absence of the protein dystrophin, is a common, degenerative muscle disease affecting 1:5000 males worldwide." (PMID 30912308, 2019). "Dystrophin is the protein that is absent in Duchenne muscular dystrophy (DMD), an X-linked fatal muscle disease, and in the mdx mouse, a DMD animal model." (PMID 31620435, 2019). "Several laboratories have worked for many years, starting with the observation of a large in-frame deletion of the dystrophin gene in patients with Becker muscular dystrophy (the milder form of Duchenne muscular dystrophy [DMD]) who were able to carry on an almost normal life." (PMID 30132372, 2018). "The first in vivo demonstration of the therapeutic AAG properties has been in mdx mice, an animal model of Duchenne muscular dystrophy (DMD), where gentamicin treatment restored 10–20% of normal dystrophin levels in the skeletal muscles." (PMID 30134808, 2018). "Duchenne muscular dystrophy (DMD) is a lethal x-linked genetic disease caused by mutations in the dystrophin gene that result in the complete lack of dystrophin protein." (PMID 29879154, 2018). "It is well-known that Duchenne muscular dystrophy (DMD) patients and dystrophin-null (mdx) mice have continuous regeneration of muscle and activation of SCs in humans and mice, respectively." (PMID 30510196, 2018). "Duchenne muscular dystrophy (DMD) is an X-linked recessive disorder caused by a lack of dystrophin, and has an overall incidence of 1 in 4700 male births." (PMID 30111310, 2018). "Duchenne muscular dystrophy (DMD) is a lethal X-linked muscle wasting disorder caused by the absence of dystrophin, a large cytoskeletal muscle protein." (PMID 29065908, 2017). "Despite promising therapeutic avenues, there is currently no effective treatment for Duchenne muscular dystrophy (DMD), a lethal monogenic disorder caused by the loss of the large cytoskeletal protein, dystrophin." (PMID 28252048, 2017). "Duchenne muscular dystrophy (DMD) is an X-linked genetic disease in which dystrophin gene is mutated, resulting in dysfunctional or absent dystrophin protein." (PMID 28845212, 2017). "Duchenne Muscular Dystrophy (DMD) is caused by a lack of dystrophin expression in patient muscle fibres." (PMID 28250438, 2017). "In addition, the partners also co-ordinate the worldwide endeavors of several laboratories developing standardized methods of dystrophin quantification, which could be used as an outcome measure in clinical trials involving Duchenne muscular dystrophy patients." (PMID 28440796, 2017). "Dystrophin/utrophin double-knockout (dKO) mice develop a more severe and progressive muscular dystrophy than the mdx mice, the most common murine model of Duchenne muscular dystrophy (DMD)." (PMID 29078808, 2017). "Duchenne muscular dystrophy (DMD) is an X-linked disease due to the absence of dystrophin in muscle that affects about one in every 3500 boys." (PMID 26798450, 2016). "Substitutions, deletions and duplications in the dystrophin gene lead to either the severe Duchenne muscular dystrophy (DMD) or mild Becker muscular dystrophy depending on whether out-of-frame or in-frame transcripts are produced." (PMID 26796035, 2016). "Duchenne muscular dystrophy (DMD) is a lethal X-linked genetic disorder (affecting approximately 1 in 5000 boys) caused by mutations in the ~2.4-megabase DMD gene which lead to irrevocable muscle wasting owing to the absence of dystrophin in the striated muscle cell lineage." (PMID 27215286, 2016). "Duchenne muscular dystrophy (DMD) is a lethal X‐linked recessive disorder caused by the lack of the cytoskeletal protein dystrophin, which leads to progressive muscle wasting and weakness." (PMID 26140505, 2015). "Duchenne muscular dystrophy (DMD), the most common and severe muscular dystrophy, is caused by the absence of dystrophin." (PMID 25907787, 2015).